CDC42SE2 (CDC42 small effector 2)
Description:
Probably involved in the organization of the actin cytoskeleton by acting downstream of CDC42, inducing actin filament assembly. Alters CDC42-induced cell shape changes. In activated T-cells, may play a role in CDC42-mediated F-actin accumulation at the immunological synapse. May play a role in early contractile events in phagocytosis in macrophages.
Synonyms: SPEC2; FLJ21967
Tractability: Antibody: its Gene Ontology location is reachable by antibodies, with high confidence; UniProt places it where antibodies can reach, with medium confidence. PROTAC: ubiquitination databases record sites on it; its protein half-life has been measured.
Gene: Protein-coding gene on chromosome 5 (131,245,493 to 131,398,447, forward strand). Ensembl gene ENSG00000158985.
Subcellular location: Cytoplasm, cytoskeleton; Cell membrane; Cell projection, phagocytic cup
Pathways (Reactome):
Signal Transduction: CDC42 GTPase cycle
Gene Ontology:
Molecular function: protein binding; signaling adaptor activity; small GTPase binding
Biological process: regulation of signal transduction; regulation of Rho protein signal transduction
Cellular component: plasma membrane; cytoskeleton; phagocytic cup
Genetic constraint (gnomAD): Loss-of-function variants: 0 observed, 1.86 expected, observed/expected ratio (o/e) 0, 90% interval 0 to 1.41. That is too few expected variants to judge how well the gene tolerates losing a copy. Missense variants: 18 observed, 29.93 expected, observed/expected ratio (o/e) 0.6, 90% interval 0.41 to 0.89. Synonymous variants: 6 observed, 9.96 expected, observed/expected ratio (o/e) 0.6, 90% interval 0.33 to 1.19.
Homologues: Orthologues: chimpanzee CDC42SE2 (100% identical), mouse Cdc42se2 (100% identical), rat Cdc42se2 (100% identical), tropical clawed frog cdc42se2l (98% identical), guinea pig CDC42SE2 (94% identical), zebrafish cdc42se2 (94% identical), pig CDC42SE2 (81% identical), dog CDC42SE2 (70% identical), macaque CDC42SE2 (69% identical), rabbit CDC42SE2 (65% identical). Paralogues in human: CDC42SE1 (46% identical).
Diseases named in the same sentence as CDC42SE2 in open-access papers:
CDC42SE2 is named in the same sentence as 8 diseases in open-access papers, as found by Europe PMC text mining. Sharing a sentence is not in itself a finding about the gene and the disease. The quoted sentences say what the papers report.
brain tumor (1 paper, 2023). "In summary, this characterized APXA CDC42SE2-BRAF fusion model will be a valuable tool for investigations in the rare brain tumor scientific community." (PMID 37280243, 2023).
CDC42SE2 also shares sentences with these, for which no sentence is quoted: cancer (2 papers); schizophrenia (2); tumor (2); asthma (1); breast carcinoma (1); infection (1); prion disease (1).